CNGA4 (cyclic nucleotide gated channel subunit alpha 4)
Description:
Pore-forming subunit of the olfactory cyclic nucleotide-gated channel. Operates in the cilia of olfactory sensory neurons where chemical stimulation of the odorant is converted to an electrical signal. Mediates odorant-induced cAMP-dependent Ca(2+) influx triggering neuron depolarization. The rise of intracellular Ca(2+) levels potentiates the olfactory response by activating Ca(2+)- dependent Cl(-) channels, but it also serves as a negative feedback signal to desensitize the channel for rapid adaptation to odorants. Conducts cAMP- and cGMP-gated ion currents, with permeability for monovalent and divalent cations.
Synonyms: OCNC2; OCNCb; CNG5; CNCA2; CNG-4; CNG4; CNGB2; OCNCBETA
Tractability: Small molecule: it belongs to a druggable protein family. Antibody: UniProt predicts a signal peptide or a membrane-spanning region; its Gene Ontology location is reachable by antibodies, with medium confidence.
Gene: Protein-coding gene on chromosome 11 (6,234,765 to 6,245,011, forward strand). Ensembl gene ENSG00000132259.
Subcellular location: Cell projection, cilium membrane
Subcellular location (Human Protein Atlas): Nucleoplasm; Plasma membrane
Pathways (Reactome):
Organelle biogenesis and maintenance: VxPx cargo-targeting to cilium
Sensory Perception: Olfactory Signaling Pathway
Gene Ontology:
Molecular function: cGMP binding; intracellularly cAMP-activated cation channel activity; intracellularly cGMP-activated cation channel activity; intracellularly cyclic nucleotide-activated monoatomic cation channel activity; monoatomic ion channel activity
Biological process: calcium ion transport; monoatomic cation transmembrane transport; potassium ion transport; sensory perception of chemical stimulus; sodium ion transport; monoatomic ion transport; transmembrane transport
Cellular component: ciliary membrane; Golgi-associated vesicle membrane; intracellular cyclic nucleotide activated cation channel complex; non-motile cilium membrane; plasma membrane; membrane
Genetic constraint (gnomAD): Loss-of-function variants: 35 observed, 50.21 expected, observed/expected ratio (o/e) 0.7, 90% interval 0.53 to 0.92. The upper end of that interval is the gene's LOEUF score, 0.92, which puts it in group 3 of 6, group 1 being the genes least tolerant of losing a copy. Missense variants: 726 observed, 792.16 expected, observed/expected ratio (o/e) 0.92, 90% interval 0.86 to 0.97. Synonymous variants: 293 observed, 320.51 expected, observed/expected ratio (o/e) 0.91, 90% interval 0.83 to 1.01.
Homologues: Orthologues: chimpanzee CNGA4 (99% identical), macaque CNGA4 (97% identical), rabbit CNGA4 (95% identical), dog CNGA4 (94% identical), rat Cnga4 (93% identical), mouse Cnga4 (93% identical), guinea pig CNGA4 (93% identical), pig CNGA4 (93% identical), tropical clawed frog cnga4 (61% identical), zebrafish cnga4 (55% identical), Drosophila melanogaster CngA (44% identical), Caenorhabditis elegans tax-4 (40% identical), and 9 more. Paralogues in human: CNGA3 (52% identical), CNGA1 (50% identical), CNGA2 (49% identical), CNGB1 (27% identical), CNGB3 (27% identical), HCN4 (23% identical), HCN1 (22% identical), HCN2 (22% identical), HCN3 (22% identical), KCNH5 (21% identical), KCNH1 (21% identical), KCNH2 (21% identical), and 5 more.
Diseases named in the same sentence as CNGA4 in open-access papers:
CNGA4 is named in the same sentence as 4 diseases in open-access papers, as found by Europe PMC text mining. Sharing a sentence is not in itself a finding about the gene and the disease. The quoted sentences say what the papers report.
virus infection (1 paper, 2025). "Two months after virus infection, the Cnga4 immunosignal was significantly reduced in the LHb in the LHb‐Cnga4 cKO mice." (PMID 40168081, 2025).
cancer (2 papers, 2018 to 2024). A tumor composed of atypical neoplastic, often pleomorphic cells that invade other tissues. "Recurrent cancer-all mutations in CNGA4 are limited to 5 distinct residues that exhibit high clustering in the Ion_trans domain." (PMID 39441719, 2024). "Since CNGA4 is important for transduction of odorant signals, it is possible that mutant proteins are advantageous to chemotaxis-mediated processes in cancer." (PMID 39441719, 2024).
CNGA4 also shares sentences with these, for which no sentence is quoted: COVID-19 (1 paper); gastric cancer (1).